MTAP (methylthioadenosine phosphorylase)
Diseases named in the same sentence as MTAP in open-access papers (continued):
Sharing a sentence is not in itself a finding about the gene and the disease.
tumor (continued). "The MTAP deleted NSCLC cohort represented the largest subset of tumor type with MTAP loss in all sequenced solid tumors." (PMID 35747993, 2023). "The concurrent biallelic loss of CDKN2A next to heterozygous MTAP gene deletion probably reflects genetic tumor progression and characterizes the spatial heterogeneity of PM." (PMID 37894345, 2023). "Based on principles of synthetic lethality, as MTAP becomes deficient in a tumor cell, its substrate methylthioadenosine (MTA) will build up." (PMID 35747993, 2023). "In vivo models have shown that MAT2a knockdown reduced the growth and development of MTAP deficient tumor cells." (PMID 35747993, 2023). "Recent study also discovered that MTAP deficiency in GBM is correlated with tumor stemness of GBM cells." (PMID 37091983, 2023). "Gross slides of these cases showed spatial loss of both p16 and MTAP, ranging from a focal loss in a smaller cell cluster to up to 50% loss in some tumor areas." (PMID 37894345, 2023). "In the present study, topographical loss of both p16 and MTAP protein in part of the tumor tissue was observed in 17% of our cases, the majority of which were WT (66%) according to CNV analysis." (PMID 37894345, 2023). "Predictors of immunotherapy efficacy were higher in MTAP‐intact versus MTAP‐lost NSCLC including tumor mutational burden (9.4 vs. 8.6 mut/Mb, p = 0.001) and low (30% vs. 28%, p = 0.01) and high PD‐L1 (32% vs. 30%, p = 0.01) expression." (PMID 35747993, 2023). "Consistent with TCGA data, IHC analysis of a tumor tissue microarray from 151 UC patients demonstrated that MTAP loss occurred in 27.8% of tumor specimens." (PMID 35379845, 2022). "An additional adenocarcinoma with homozygous deletion of CDKN2A showed loss of mTAP expression in a subset of the tumor." (PMID 35565429, 2022). "The correlations of MTAP expression with various clinicopathological features were investigated and the results showed that low expression of MTAP was significantly positively associated with tumor recurrence (P=0.0261)." (PMID 35541910, 2022). "Tumors with MTAP deletion develop increased levels of intracellular arginine, which renders them susceptible to anti-tumor therapeutic approaches based on a synthetic lethality mechanism." (PMID 35881043, 2022). "In a similar manner, others have considered the potential role of the tumor microenvironment in therapy directed against MTAP-deficient cells." (PMID 35806160, 2022). "The expression of MTAP, another tumor suppressor at 9p21.3, was strongly associated with SCNAs and tumor progression, although its mean level was similar to that in the normal tissue." (PMID 35677048, 2022). "Multiple clinical trials are currently being conducted which are focused on PRMT5 or MTA2 inhibition designed to take advantage of the high intracellular arginine levels in the MTAP deficient tumor cells." (PMID 35881043, 2022). "Clinical trials having NCT identifiers NCT00062283 and NCT00075894 use anitibiotic l-alanosine as an inhibitor for MTAP-deficient tumor cells." (PMID 36572880, 2022). "MTAP, a tumor suppressor gene, encodes a key rate-limiting metabolic enzyme required for the metabolism of polyamines and purines and has a major function in the purine/methionine salvage pathway." (PMID 36572880, 2022). "Of particular interest in developing therapies that capitalize on aberrant tumor metabolism is collateral deletion of the evolutionarily conserved metabolic enzyme methylthioadenosine phosphorylase (encoded by MTAP)." (PMID 34244484, 2021). "MTAP-deficient tumor cells accumulate high levels of MTA leading to a reduced PRMT5 activity, which renders these cells more susceptible toward additional PRMT5 inhibition compared to MTAP-competent cells." (PMID 33123121, 2020). "The deletion of this region usually causes co-deletion of MTAP and some classic and well-known tumor suppressor genes such as CDKN2A/B." (PMID 32093414, 2020).
tumor (continued). "A subset of MPM tumours show loss of the methyladenosine phosphorylase (MTAP) locus, resulting in profound alterations in polyamine metabolism, ATP and methionine salvage pathways, as well as changes in epigenetic control of gene expression." (PMID 31819191, 2020). "MTAP-deficient tumor cells are more susceptible toward PRMT5 inhibition than MTAP-competent ones, so using PRMT5 inhibitors is an opportunity to specifically target this tumor cell group." (PMID 33123121, 2020). "It is important to note that in some cases, there are some samples with <10% of tumor that shows MTAP IHC loss, but the numbers of these cases are small (3/72) in the entire analyzed cohort." (PMID 33304846, 2020). "5′-Deoxy-5′-methylthioadenosine (MTA) phosphorylase (MTAP) deficiency in tumors results in the accumulation of MTA within the tumor microenvironment and thereby negatively influencing immune functions of various immune cells, including T and NK cells." (PMID 33123121, 2020). "MTAP-deficient tumor cells are more sensitive to inhibitors of de novo purine synthesis than cells with intact MTAP11." (PMID 31965001, 2020). "Adenine is phosphoribosylated by adenine phosphoribosyltransferase to form AMP, thus competitively inhibiting phosphoribosylation of 6-TG to a toxic nucleotide, and protecting normal cells while killing MTAP-deficient tumor cells." (PMID 31284411, 2019). "In our clinical observations, we show that a significant percentage of RCC tumors have low MTAP expression and that MTAP expression is inversely associated with tumor grade and shortens patient survival." (PMID 30701095, 2019). "A treatment strategy combining methylthioadenosine (MTA) with 6-TG has been proven successful in selectively killing MTAP-deficient tumor cells." (PMID 31284411, 2019). "Our results show that MTAP expression inhibits several tumor-related phenotypes and causes global changes in gene expression, affecting several cellular pathways controlling cell adhesion and signaling." (PMID 25387827, 2014). "Loss rates range from 14% to 100% depending on the tumor type and the method used to assess MTAP loss." (PMID 23840755, 2013). "A potential mechanism by which loss of MTAP enhances tumor formation involves the link between MTAP and polyamine metabolism." (PMID 23840755, 2013). "Despite the knowledge that loss of MTAP expression is a relatively frequent event in a variety of different tumor types, the biological importance of MTAP loss in tumorigenesis has only recently started to be addressed." (PMID 23840755, 2013). "Loss at MTAP (P = 0.05) and the interferon gene cluster (P = 0.03) on 9p21 was also associated with tumor ulceration." (PMID 20140953, 2010). "In malignant melanoma, loss of MTAP-expression is also common – with one report placing it as high as 60% – but in this tumor the deficiency appears to be due to promoter hypermethylation." (PMID 19478948, 2009). "All MTAP-deleted tumors were microsatellite stable and low tumor mutational burden (TMB-low)." (PMID 41899498, 2026). "Loss of the MTAP gene increases the dependence of MTAP‐deleted tumours on PRMT5." (PMID 41537447, 2026). "MTAP IHC is a near perfect surrogate for MTAP deficiency in this tumor type." (PMID 39668577, 2025). "Indeed, our experience demonstrated an appropriate specificity of MTAP IHC when complete loss versus more than 1% of tumour cell expression was observed." (PMID 40566743, 2025). "Several studies highlight the impact of MTAP loss on tumor growth and aggressiveness." (PMID 41439984, 2025). "Homozygous MTAP loss was the main deleterious alteration retrieved (22/27, 81.5%), followed by mutations (5/27, 18.5%), although differences were noticed according to primary tumour histology." (PMID 38350716, 2025). "In vivo, pemetrexed was found to have anti-tumor effects on MTAP-deficient xenograft models." (PMID 41439984, 2025).
tumor (continued). "Additionally, MTA accumulation and PRMT inhibition through loss of MTAP function promoted extracellular signal-regulated kinase (ERK)-mediated tumor metastasis in melanomas." (PMID 41439984, 2025). "In line with our data, these authors found MTAP deficiency in 22% of their patients, identified tumor‐adjacent dysplastic urothelium solely on the basis of unequivocal MTAP negativity in several cases, and found persistent MTAP deficiency in 37 of 38 subsequent recurrences." (PMID 39668577, 2025). "MTAP deficiency is currently one of the most promising molecular targets for tumor therapies." (PMID 40227771, 2025). "Notably, MTAP‐deficient tumors caused MTA accumulation in the tumor microenvironment, which impaired T‐cell function through PRMT5 inhibition and adenosine receptor agonism in T‐cells, ultimately attenuating the effects of immune checkpoint inhibitors." (PMID 40552664, 2025). "All tumour types but CRC were characterised by gene loss as the only MTAP genetic alteration." (PMID 38350716, 2025). "Consequently, MTA accumulates in the microenvironment of MTAP-deficient tumors, where it is known to inhibit tumor-infiltrating T cells and NK cells." (PMID 39768204, 2024). "Consequently, MTAP-deficient tumors accumulate MTA in the tumor microenvironment, which is associated with remodeling the intra-tumoral immune landscape towards a pro-tumoral phenotype." (PMID 39768204, 2024). "Here, we undertook a cross-sectional study of >64 000 tumor profiles across the 5 most common GI cancer types to establish the prevalence of MTAP-loss, describe genomic differences between MTAP-loss and MTAP-intact tumors, and delineate any intersection with established immunotherapy markers." (PMID 38330461, 2024). "In MTAP-deficient cells, lower sDMA modification on protein reduces the degradation of vimentin, therefore increasing vimentin expression and ultimately enhancing tumor metastasis." (PMID 37091983, 2023). "Tumor cells with MTAP mutation had fewer CD8+ T cells in TME." (PMID 36860322, 2023). "In such cases, the detection of copy-number loss by p16 FISH, especially of those tumor aggregates showing loss of both p16 and MTAP, may help to determine the malignant nature of the mesothelial proliferation." (PMID 37894345, 2023). "This metabolite accumulation in MTAP-deficient tumor cells led to sensitivity to PRMT5 targeting." (PMID 37091983, 2023). "The overall frequency of MTAP loss in all tumor types was 9.4%." (PMID 35747993, 2023). "It has been shown that malignant tumor cell lines with MTAP deficiency could be targeted when purine synthesis was blocked and MTA was the only exogenous source of purines." (PMID 37091983, 2023). "It is believed that only a small number of tumor-specific metabolic vulnerabilities have been successfully targeted, and that many potential targeted therapies are under investigation, including therapies targeting MTAP deficiency." (PMID 36913304, 2023). "Besides, another study focusing on the genomic profiling and functional characterization of tumor cell lines revealed that MTAP loss relied on PRMT5." (PMID 37091983, 2023). "The increased levels in tumor cells may be ascribed to the lower level of MTA phosphorylase (MTAP) or the loss of MTAP activity, which converts MTA into 5-methylthioribose-1-phosphateandadenine." (PMID 35209071, 2022). "In addition, a potential strategy for therapeutically depriving purine supply in MTAP-deficient tumor cells is to target enzymes in the de novo purine synthesis pathway." (PMID 35453502, 2022). "The post-hoc analysis of MTAP IHC revealed the loss of expression in 44% of tumors with a significant association of better clinical outcome compared to MTAP-positive tumors (median change of tumor volume −18% vs. 0%)." (PMID 36362209, 2022). "The loss of MTAP expression has been linked to a tumor-promoting effect in multiple cancers, and MTAP may serve as a tumor suppressor." (PMID 35979371, 2022).
tumor (continued). "Collectively, our data support the hypothesis that tumor MTAP deficiency creates a metabolic vulnerability for therapy with antifolate agents such as pemetrexed." (PMID 35379845, 2022). "As such, tumor MTAP deficiency may provide a metabolic vulnerability for the use of antifolate agents such as pemetrexed to effectively treat UC with 9p21 loss." (PMID 35379845, 2022). "Specific targeting of MTA metabolism in MTAP-deficient tumors therefore could offer a promising new strategy to reverse immune dysfunction of NK cells within the tumor microenvironment." (PMID 33123121, 2020). "The conflicting result, that is a good response but with poor survival, suggested that there may be other pathways affecting the sensitivity of MTAP-deficient tumor cells to pemetrexed." (PMID 31965001, 2020). "Loss of MTAP expression in tumor cells results in the accumulation of MTA." (PMID 33123121, 2020). "Though there are challenges and advantages of targeting tumors which lack MTAP activity, MTAP deficiency in human GBM could be a potential target for tumor-specific chemotherapy." (PMID 29164057, 2017). "MTAP has also been implicated as a possible tumor suppressor." (PMID 25917288, 2015). "Because MTA is a competitive inhibitor of methyltransferase enzymes, including histone and DNA methyltransferases, it is possible that loss of MTAP may have effects on the epigenetic control of gene expression in tumor cells." (PMID 25387827, 2014). "Moreover, MTAP deletion has been associated with specific molecular and immunologic profiles that may influence treatment response and tumor microenvironment characteristics." (PMID 41465382, 2025). "Future mechanistic studies are warranted to define how MTAP deficiency alters tumor glutamate metabolism to suppress CXCL10 expression, and whether CB-839-mediated upregulation of CXCL10 is sufficient to restore T cell infiltration and activation in MTAP-deficient tumors." (PMID 41246302, 2025). "However, if MTAP‐deficient tumor cells are surrounded by MTAP‐expressing normal cells, they may metabolize the secreted MTA, thus diminishing the synthetic lethal effect of MTAP‐deficient cells." (PMID 39711357, 2024). "We next evaluated whether MTAP expression is associated with RCC tumor grade." (PMID 30701095, 2019). "Loss of MTAP leads to the accumulation of 5'-methylthioadenosine (MTA), which sensitizes tumor cells to inhibition of protein arginine methyltransferase 5 (PRMT5)." (PMID 42150143, 2026). "In contrast, second‐generation PRMT5 inhibitors selectively bind the PRMT5–MTA complex and preferentially target MTAP‐deleted tumour cells." (PMID 41537447, 2026). "By day 21, tumors derived from MTAP-KO cells exhibited significantly accelerated growth and greater tumor volume compared to their WT counterparts." (PMID 41246302, 2025). "MTAP deletion in tumor cells leads to the accumulation of MTA in the microenvironment, which negatively impacts PRMT5 activity in T cells, as elevated MTA levels suppress its function." (PMID 39983717, 2025). "MTAP deficiency leads to the accumulation of methylthioadenosine (MTA) in tumor cells, which in turn accelerates malignant tumor progression." (PMID 41281760, 2025). "Enrichment for MTAP loss was confirmed in a subset of tumour types, that is, PC and GEC (p<0.001), while CRC was confirmed as far less represented in the MTAP loss population as compared with the unaltered one (p<0.001)." (PMID 38350716, 2025). "AMG 193 is an MTA-cooperative PRMT5 inhibitor in vitro, AMG 193 preferentially inhibited the MTA-bound PRMT5 enzyme in tumor cells with MTAP deletion." (PMID 41465382, 2025).
tumor (continued). "The scientific world is grappling with BAP1, MTAP, and the tumour inflammatory microenvironment, because they are the key for personalized treatments and palliative care in this disease." (PMID 40506895, 2025). "This suggests that MTAP plays a critical role in shaping tumor immunogenicity through regulation of interferon-driven chemokine expression." (PMID 41246302, 2025). "Preclinical and early clinical data indicate that targeting these pathways can selectively impair tumor growth while sparing MTAP-proficient cells." (PMID 41465382, 2025). "Recent research indicates that MTAP-deleted tumor cells exhibit specific vulnerabilities to MAT2A inhibition." (PMID 39983717, 2025). "CDKN2A/B co‐mutations were significantly represented in tumours with STK11 (63%, 10/16, p = 0.024), KEAP1 (59%, 10/17, p = 0.045), and SPEN (90%, 9/10, p < 0.001) alterations, and in all tumours with MTAP alterations (100%, 16/16, p < 0.001)." (PMID 41015991, 2025). "On the other hand, lack of adenine leads to a high level of PRPP and conversion of 2-FA into its toxic nucleotide in MTAP-null tumors, thus killing the tumor cells." (PMID 41439984, 2025). "Treatment, especially with PARPi, resulted in an enhanced tumor growth inhibition in MTAP-null xenografts." (PMID 40590219, 2025). "Strikingly, the relationship between MTAP expression and aggressive tumor phenotype became much clearer in these subgroups although inverse relations were observed." (PMID 40554389, 2025). "While CDKN2A/B genes have been established as tumor suppressor genes, the role of MTAP in tumorigenesis has seen contradicting perspectives." (PMID 41439984, 2025). "In GI cancers, MTAP-deleted tumor sections demonstrate epithelioid histology with higher mitotic rate." (PMID 41439984, 2025). "Several other purine analogs have been studied on MTAP-deleted tumors, including 6-thioguanine that targets de novo purine synthesis and kills tumor cells by incorporating 6-thioguanine nucleotides into DNA." (PMID 41439984, 2025). "AG-270, a highly active MAT2A inhibitor, has been reported to effectively inhibit the growth of a variety of MTAP-null tumor cells, including non-small cell lung cancer, PC and bladder cancer." (PMID 41281760, 2025). "The MTAP protein is encoded by the MTAP gene located at chromosome 9p21, near the CDKN2A gene, whose homozygous deletion is observed in a wide range of neoplasms, particularly in MPM, where it occurs in over 70% of cases." (PMID 39941848, 2025). "BMS-986504 induced activation of cytotoxic T lymphocytes and increased PD-L1 expression on MTAP deletion tumor cells." (PMID 41465382, 2025). "Accumulating evidence has demonstrated the role of MTAP in regulating tumor migration and invasion through different mechanisms." (PMID 41439984, 2025). "Case #3, which displayed hemizygous loss of CDKN2A/MTAP on MIP, demonstrated focal positivity for both p16 and MTAP in less than 25% of the tumor tissue." (PMID 40227557, 2025). "This epigenetic rewiring can shift the balance between oncogenic and tumor-suppressive transcriptional networks, sensitizing MTAP-deleted cells to further perturbation of PRMT5 or its upstream regulator MAT2A." (PMID 41465382, 2025). "Mice were implanted contralaterally on their flanks with parental and MTAP-deleted HCT116 cells such that each mouse would carry one WT and one MTAP-deleted tumor." (PMID 40377999, 2025). "For example, protein arginine methyltransferase 5 (PRMT5) inhibitor EZP015556 effectively inhibited both methylthioadenosine phosphorylase (MTAP)- and MTAP+ tumor organoids, both of which were hallmarked by high 5'-methylthioadenosine (MTA) levels." (PMID 38250041, 2024).